GPX4 (glutathione peroxidase 4)
Diseases named in the same sentence as GPX4 in open-access papers (continued):
Sharing a sentence is not in itself a finding about the gene and the disease.
glioma (continued). "Subsequent HSPA5 upregulation increased the expression and activity of glutathione peroxidase 4 (GPX4), which neutralized DHA-induced lipid peroxidation and thus protected glioma cells from ferroptosis." (PMID 31519193, 2019). "We have previously explored the potential mechanism of genetically engineered bacteria Salmonella YB1 in the treatment of glioma and found that Salmonella YB1 inhibits the expression of glutathione peroxidase-4 and induces ferroptosis to suppress glioma growth." (PMID 39660865, 2025). "Moreover, high expression of TRIM26, GPX4 and PLK1 was correlated with poor survival in patients with glioma." (PMID 37872147, 2023). "In the present investigation, we found that SLC39A14 silencing may promote erastin-induced ferroptosis in glioma by modulating the levels of MDA, Fe2+, GSH, GPX4, NRF2, and SLC7A11, which may further inhibit the progression of gliomas." (PMID 37978473, 2023). "The 63‐induced drop of GPX4 and GSH and increase in MDA levels was reduced by ferrostatin‐1, which suggests that 63 combines low micromolar cytostatic activity with a moderate potential to induce ferroptosis in glioma cells." (PMID 36658724, 2023). "Finally, we performed an IHC assay on 83 human glioma samples, and observed that TRIM26 expression was positively correlated with GPX4 and PLK1 protein levels." (PMID 37872147, 2023). "Similarly, other results have demonstrated that the U87MG cell line was sensitive to ferroptosis induced by the direct inhibition of GPX4 by RSL3 treatment, and murine glioma GL261 cells died through ferroptosis after RSL3 stimulation." (PMID 35805884, 2022). "In summary, this study demonstrated that paeoniflorin might function as an effective drug for glioma by inducing ferroptosis via upregulation of NEDD4L and repression of Nrl2, GPX4, and STAT3." (PMID 36618071, 2022). "Low expression of GPX4 and high expression of HMOX1 were identified in DHA treated glioma cells." (PMID 36164395, 2022). "Additionally, the expression of GCH1 and FSP1 increased with increasing malignancy of the tumor; GPX4, FSP1, and GCH1 were highly expressed in patients with glioma and wild-type IDH1 compared to mutant IDH1." (PMID 35174170, 2021). "After overexpression of ACSL4, the GPX4 expression was significantly reduced, whereas the expression of ferroptosis indicators 5-HETE, 12-HETE, and 15-HETE significantly increased, thus inhibiting the proliferation of glioma cells." (PMID 34944434, 2021). "The analysis of mRNA expression profiles of glioma samples and non-tumor brain tissues provided evidence that GPX4, FSP1, and DHODH were highly expressed in tumoral tissue compared to that in non-tumor brain tissues." (PMID 35174170, 2021). "The expression of GPX4 in gliomas increases with the increasing grades of gliomas, and the expression of GPX suppressed by siRNA can inhibit the proliferation and migration of glioma cells." (PMID 32656078, 2020). "Given that GPX4 is the critical enzyme that reduces lipid peroxidation to prevent ferroptosis, we thus assessed the roles of GPX4 in HSPA5-mediated ferroptotic resistance against DHA in glioma cells." (PMID 31519193, 2019). "Oppositely, enhanced IRF2 in gliomas may interfere with SLC7A11 and GPX4 to extinguish ferroptosis." (PMID 39309434, 2024). "Consequently, orexin‐A may induce ferroptosis in gliomas by selectively targeting NFE2L2 and regulating the downstream expression of GPX4, TFRC and FTH1." (PMID 38685674, 2024). "However, in our study, we found that SLC1A5 was the suppressor of ferroptosis in glioma and overexpression of SLC1A5 could increase the expression of GPX4." (PMID 36566214, 2022). "Lastly, the dependency on GPX4 yet not SLC7A11 in both mouse models may suggest that glioma cells obtain cysteine independent of the system xc− antiporter, such as the transsulfuration pathway, while still depending on robust GPX4 activity to eliminate lethal concentrations of lipid peroxides." (PMID 39192032, 2024).
glioma (continued). "Notably, GPX4 restoration significantly counteracted with the enhancement of DHA-induced ROS, MDA and lipid ROS production as well as cell death rate by HSPA5 silencing in both U251 and U373 cells, suggesting that GPX4 mediated the anti-ferroptotic effects of HSPA5 against DHA in glioma cells." (PMID 31519193, 2019). "GPX4, FSP1, and GCH1 were highly expressed, while DHODH expression was low in patients with gliomas with a 1p19q non-codeletion compared to those with a 1p19q codeletion." (PMID 35174170, 2021). "Our analysis showed that GPX4, FSP1, GCH1, and DHODH were more highly expressed in tumor tissue than in non-tumor brain tissue, especially in high-grade, IDH1 wild type, 1p19q non-codeletion gliomas, suggesting that glioma cells had a strong potential to resist ferroptosis." (PMID 35174170, 2021).
pancreatic cancer (81 papers, 2018 to 2026). "Both rapamycin (classical autophagy inducer) and RSL3 can block mechanistic target of rapamycin kinase (MTOR) activation and cause GPX4 protein degradation in human pancreatic cancer cells, which can restore or enhance the anticancer activity of gemcitabine in vitro or in xenogeneic PDAC models." (PMID 36105219, 2022). "This may be related to increased reactive oxygen species (ROS) production and activation of fatty acid synthesis, such as via fatty acid synthetase, and pancreatic cancers with KRAS mutations may be expected to have increased lipid peroxidation from GPX4 inhibition." (PMID 39858464, 2025). "A group led by Yuan Wang demonstrated that the acetylation of HSPA5 by EP300 amplified the HSPA5-induced suppression of GPX4, leading to heightened lipid peroxidation and ferroptosis in pancreatic cancer." (PMID 40255561, 2025). "Results from another study demonstrates that thiostrepton induces ferroptosis via Stat3/GPX4 axis in pancreatic cancer cells." (PMID 41341590, 2025). "TST induces ferroptosis in pancreatic cancer cells by inhibiting GPX4 expression through the STAT3/GPX4 signaling pathway, leading to iron overload and lipid peroxidation." (PMID 40733146, 2025). "Promotion of cancer cell survival: GPX4 activity is essential for the survival of many cancer cells, including pancreatic cancer cells." (PMID 39858464, 2025). "As a molecular sponge, circ_WASF2 promotes pancreatic cancer progression by regulating the miR-634/GPX4 signaling pathway." (PMID 40403492, 2025). "TST strongly decreases STAT3 protein expression and phosphorylation, limiting GPX4 transcription and enhancing ferroptosis in pancreatic cancer cells, according to western blot tests." (PMID 40969276, 2025). "The following are possible reasons why pancreatic cancer cells show resistance to ferroptosis due to GPX4 inhibition: high expression of FSP1, low expression of OPA1, and impaired autophagy function." (PMID 39858464, 2025). "The predictive survival rate of patients with pancreatic cancer can be significantly increased by the high expression of GPX4 in these cells." (PMID 40969276, 2025). "Among the potential downstream effectors, STAT3 has been reported to modulate GPX4 transcription in pancreatic cancer cells." (PMID 41166024, 2025). "Copper ions increase the autophagic degradation of GPX4 by directly binding to Cys107/148 of GPX4 protein, leading to ferroptosis in pancreatic cancer cells." (PMID 39624080, 2024). "In pancreatic cancer, glutamine deprivation has been shown to reduce GPX4 expression, a central regulator of ferroptosis, thus sensitizing cells to ferroptosis through the KRAS/MAPK-NRF2-GPX4 pathway." (PMID 39518098, 2024). "In pancreatic cancer cells, circ_WASF2 is significantly overexpressed, promoting pancreatic cancer cell proliferation by targeting the miR-634/GPX4 axis." (PMID 38994627, 2024). "The upregulated levels of IL15RA, ACSL3 and GPX4 in pancreatic cancer cells were verified by qRT-PCR and western blot analysis." (PMID 39396119, 2024). "Current research is focusing on the development of small-molecule inhibitors of GPx4 as potential candidates for pancreatic cancer treatment." (PMID 39594547, 2024). "For instance, depleting Gpx4 in the pancreas or using high-iron diets in studies involving caerulein-induced pancreatitis and KrasG12D-induced pancreatic cancer in mice accelerated experimental pancreatitis and tumorigenesis." (PMID 38844964, 2024). "Studies have shown that Stat3 binds to the promoter region of Gpx4 and activates its transcription, thereby inhibiting ferroptosis in pancreatic cancer cells." (PMID 38803032, 2024). "The inhibition of GPx4 can trigger ferroptosis selectively in cancer cells, especially in those that rely heavily on this pathway for survival, such as pancreatic cancer cells." (PMID 39594547, 2024).
pancreatic cancer (continued). "Immunohistochemical staining of HMGA2 and GPX4 in 63 pancreatic cancer tissue chip samples revealed intense GPX4 staining in high HMGA2-expressing samples." (PMID 38493165, 2024). "Selenomethionine increased GPx4 protein and activity in pancreatic cancer and reversed P-AscH−-induced toxicity and lipid peroxidation." (PMID 38539894, 2024). "In this study, we demonstrated that HMGA2 promotes pancreatic cancer cell growth and exhibits antiferroptotic effects by activating the mTORC1 pathway and enhancing GPX4 translation." (PMID 38493165, 2024). "It is worth noting that the existing results show that the knockout of Slc7a11 and Gpx4 in distinct mouse models of pancreatic cancer have different results in the process of pancreatic cancer." (PMID 39769097, 2024). "In pancreatic cancer cells, loss of TXNRD1 results in increased abundance of GPX4 protein, and confers protection from ferroptosis." (PMID 35805147, 2022). "In conclusion, our study identified the mechanism by which TST-induced ferroptosis in pancreatic cancer cells through STAT3/GPX4 signalling." (PMID 35859150, 2022). "RSL-3 can block the mTOR activation to promote GPX4 protein degradation in pancreatic cancer cells, which facilitates the autophagy-dependent ferroptosis induced by RSL-3." (PMID 36570007, 2022). "An important mechanism of chemotherapy sensitization is to reduce the expression of GPX4 in pancreatic cancer cells." (PMID 35859150, 2022). "GSH is an antioxidant in the form of a tripeptide that acts as a synergistic molecule for selenium-dependent GPX4 and assists GPX4 in reducing lipid hydroperoxides, thus mediating ferroptosis resistance in pancreatic cancer cells." (PMID 35693705, 2022). "Compared to normal tissues, mRNA levels of OTUB1, SLC7A11 and GPX4 were significantly upregulated in pancreatic cancer tissues." (PMID 35494004, 2022). "In 2012, a novel regulated cell death pathway-ferroptosis was discovered by studying the pancreatic cancer; the process is characterized by loss of intracellular glutathione (GSH) and the inactivation of glutathione peroxidase 4 (Gpx4)." (PMID 33646533, 2021). "The overall survival analysis showed that high GPX4 expression is related to the increased survival rate of pancreatic cancer patients (high-expression GPX4 group: n = 131; low-expression GPX4 group: n = 43)." (PMID 34503532, 2021). "Other studies have found that the expression of the GPX4 gene in the pancreatic cancer group is upregulated compared with that in the normal group using TCGA database analysis." (PMID 34503532, 2021). "It has been reported that erastin promotes the degradation of GPX4 via CMA, and that RSL3 can block mTOR activation and cause GPX4 degradation in pancreatic cancer cells." (PMID 34716292, 2021). "Tumor-associated macrophages (TAMs) were increased in Kras-driven mice with Gpx4 depletion or a high-iron diet, indicating that iron and GPX4 are regulators of macrophage infiltration in pancreatic tumor microenvironment." (PMID 33311482, 2020). "CONCLUSIONS: Dronedarone serves as an unrecognized promoter of ferroptosis in pancreatic cancer by targeting p62-mediated autophagic degradation and functional inactivation of GPX4, providing a mechanistic and translational rationale for exploiting ferroptosis in pancreatic cancer." (PMID 41832527, 2026). "In neurological disorders, ferroptosis contributes to PD progression by causing mitochondrial dysfunction in dopaminergic neurons, while in oncology, this process significantly suppresses pancreatic cancer development through modulation of key proteins like GPX4." (PMID 40919133, 2025). "In summary, GPX4 may play a significant role in the development and occurrence of pancreatic cancer." (PMID 40969276, 2025).
pancreatic cancer (continued). "Treatment resistance: pancreatic cancer cells with high GPX4 expression and activity may be resistant to treatments that induce ferroptosis." (PMID 39858464, 2025). "Moreover, the dataset equally confirmed recently published data demonstrating that GPX4 targeting is inefficient in pancreatic cancer." (PMID 41173858, 2025). "Similarly, exogenous copper has been observed to increase GPX4 ubiquitination and facilitate TAX1BP1 (Tax1 binding protein 1)-dependent GPX4 autophagic degradation, thereby enhancing ferroptosis in pancreatic cancer tumors." (PMID 39856053, 2025). "Furthermore, HSPA5 is a molecular chaperone associated with endoplasmic reticulum stress that can bind to GPX4 to inhibit protein kinase-induced degradation of GPX4, thereby suppressing ferroptosis in pancreatic cancer cells." (PMID 39021564, 2024). "Mechanistically, STAT3 binds to GPX4 and regulates its expression in pancreatic cancer cells." (PMID 38575966, 2024). "However, thiostepton can inhibit STAT3 and GPX4 signaling to induce ferroptosis in pancreatic cancer cells, which is inconsistent with our findings." (PMID 38444939, 2024). "By regulating PIR expression, MCP exerts dual biological effects: it induces ferroptosis in pancreatic cancer cells by suppressing GPX4 and promotes macrophage pro‐inflammatory M1‐like polarization by enhancing cytoplasmic translocation and the early release of HMGB1." (PMID 38593415, 2024). "In addition, wogonin decreases GSH levels in cells via the Nrf2-mediated GPX4 pathway, thereby further enhancing lipid peroxidation and ROS accumulation in pancreatic cancer cells." (PMID 36909174, 2023). "In addition, the interaction of rapamycin kinase (mTOR) mechanism target signal and glutathione peroxidase 4 (GPX4) signal can regulate autophagy-dependent ferroptosis in human pancreatic cancer cells." (PMID 35057861, 2022). "The predictive powers of OTUB1, SLC7A11 and GPX4 in pancreatic cancer were highly accurate." (PMID 35494004, 2022). "Lipid peroxidases inhibit GPx4 and stimulate pancreatic cancer development." (PMID 35208621, 2022). "Furthermore, bioinformatic analysis showed that system Xc− (SLC3A2 and SLC7A11) and GPX4, the major negative regulators of ferroptosis, were upregulated in gemcitabine-resistant pancreatic cancer cells." (PMID 35530337, 2022). "Degradation of GPX4 by sulfasalazine has been also reported in breast and pancreatic cancer cells." (PMID 34572979, 2021). "Further mechanistic studies have shown that DIPAH3 inhibition promotes the antioxidant effect mediated by TrxR1 and GPX4, the key factors of selenium metabolism, increases the levels of peroxides and ROS, and ultimately inhibits the malignant phenotype of pancreatic cancer." (PMID 34503532, 2021). "It is reported that ROS accumulation is promoted following oxidative stress exposure to either H2O2 or erastin during GPX4 knockdown, and overexpression of GPX4 eliminates the oxidative stress, thereby protecting physiological processes in human pancreatic cancer cells." (PMID 34745435, 2021). "Hence, we treated pancreatic cancer cells with RSL3 (a well-known ferroptosis inducer that inhibits GPX4) in the presence of Wortmannin (WM, a well-known autophagosome inhibitor that supresses autophagosome) or Rapamycin (RA, a well-known autophagy activator that inhibits mTOR)." (PMID 36248959, 2022).